SHC1 (SHC adaptor protein 1)
Diseases named in the same sentence as SHC1 in open-access papers (continued):
Sharing a sentence is not in itself a finding about the gene and the disease.
liver cancer (2 papers, 2022 to 2024). An epithelial or non-epithelial malignant neoplasm that arises from the liver. "SHC1 expression was associated with five MMR genes in human pan-cancers, especially in liver cancer." (PMID 35601500, 2022). "Functional genes, e.g., Akt1, Shc1, Prkce, Jun, and Hdac1, were highly related to each other and might play important regulatory roles in the accelerated liver cancer initiation in Zbtb7bΔli livers." (PMID 38225233, 2024).
melanoma (2 papers, 2020 to 2022). A malignant, usually aggressive tumor composed of atypical, neoplastic melanocytes. "These genes contained KDELR3, EIF4EBP1, TARS, MTHFD2, SHC1 which all highly expressed in melanoma compared to normal skin in The Human Protein Atlas." (PMID 33136551, 2020). "In this research, we further distinguished 5 differentially expressed UPRRGs (KDELR3, EIF4EBP1, TARS, MTHFD2 and SHC1), which also highly expressed in melanoma at the protein level." (PMID 33136551, 2020).
acute leukemia (1 paper, 2019). A clonal (malignant) hematopoietic disorder with an acute onset, affecting the bone marrow and the peripheral blood. "However, FRYL is an important gene in therapy‐related acute leukemias, while KIAA1683 and SHC1 might be novel cancer genes." (PMID 30828525, 2019).
age-related macular degeneration (1 paper, 2021). Age-related loss of vision in the central portion of the retina (macula), secondary to retinal degeneration. "WEE1, SMC2, HMGB1, RRM2, and POLA1 proteins were also observed to be involved in the progression and invasion of retinoblastoma; SLC24A2 and DTX4 in age-related macular degeneration; and EPHB6, EFNB3, and SHC1 in glaucoma." (PMID 34646884, 2021).
angiosarcoma (1 paper, 2024). A malignant tumor arising from the endothelial cells of the blood vessels. "Hierarchical classification finds the similarity of proteomic features between angiosarcoma and epithelial sarcoma, and elevated expression of SHC1 in AS and ES is correlated with poor prognosis." (PMID 38360860, 2024).
autoimmune thyroid disease (1 paper, 2024). Inflammatory disease of the thyroid gland due to autoimmune responses leading to lymphocytic infiltration of the gland. "GSEA of the hub gene SHC1 was predominantly enriched in allograft rejection, autoimmune thyroid disease, leishmania infection, toll-like receptor (TLR) signaling pathway, and type I diabetes mellitus." (PMID 39391879, 2024).
B-cell CLL (1 paper, 2016). "Similarly, activation of serine/threonine-protein kinases (Akt2 and Akt3) in combination with B-cell CLL/lymphoma (Bcl2), collagen (COL4A1), Src transforming protein (SHC1) lead to the activation of focal adhesion pathway." (PMID 27367858, 2016).
bone osteosarcoma (1 paper, 2020). A usually aggressive malignant bone-forming mesenchymal neoplasm arising from the bone. "Interestingly, in a proteome wide study of PARylated proteins present in human bone osteosarcoma-derived UOS2 cells that do not express SHC3, the closely related protein SHC1 was identified as PARP1 target." (PMID 32443613, 2020).
chronic myeloid leukemia (1 paper, 2019).
glomerular diseases (1 paper, 2017). "SHC1 and PRCP presented weak (+) staining in control kidney tissue and weak (+) to strong (+++) staining in the samples of other glomerular diseases and in the IgAN group." (PMID 28831120, 2017). "Immunohistochemistry staining for validation targets, CAP1, SHC1 and PRCP, was performed on eight IgAN, three other glomerular diseases and one healthy control slides of kidney tissue." (PMID 28831120, 2017).
hypertensive nephropathy (1 paper, 2021). Kidney damage that results from chronically elevated blood pressure; complications include glomerular damage resulting in proteinuria and hematuria. "More recently, the SH2 adaptor protein P66SHC (encoded by Shc1) was found to regulate renal vascular tone in hypertensive nephropathy." (PMID 33377622, 2021). "Although a sequence variant in Shc1 has yet to be identified in Dahl S rats relative to other strains, these results suggest a role for P66SHC as a potential new candidate pathway that impairs renal vascular tone in Dahl S rats and contributes to hypertensive nephropathy." (PMID 33377622, 2021).
Hypoglycemia (1 paper, 2017). A decreased concentration of glucose in the blood. "It will be interesting to investigate if the expression of the genes encoding MCKAT (ACAA2) or its inhibitor SHC1 might differentiate between MCAD-deficient patients that presented with hypoketotic hypoglycemia and those that never did." (PMID 28369071, 2017).
lipoidosis (1 paper, 2026). "In addition, lung neoplasms were associated with AKT1, lipoidosis was associated with ASNS, and drug-induced acute liver injury was associated with SHC1." (PMID 42065147, 2026).
microcephaly (1 paper, 2025). A congenital or acquired developmental disorder in which the circumference of the head is smaller than normal for the person's age and sex. "The two existing in vivo studies investigating SHC1 disruption in mouse brains consistently observed microcephaly, yet intriguingly reported different underlying mechanisms for this abnormal brain development." (PMID 40593476, 2025). "Moreover, the inactivation of SHC1 through mutations in its tyrosine phosphorylation sites has been associated with the depletion of the NSC pool and the development of microcephaly, driven by increased NSC apoptosis." (PMID 40593476, 2025).
osteoporosis (1 paper, 2015). A condition of reduced bone mass, with decreased cortical thickness and a decrease in the number and size of the trabeculae of cancellous bone (but normal chemical composition), resulting in increased fracture incidence. "The results of the current study also showed that CTNNB1 and CAV1 were significantly downregulated in the osteoporosis samples, while SHC1, AKT1 and FLNA were upregulated." (PMID 25815782, 2015).
prostate tumor (1 paper, 2022). "The expression of SHC1 was found to be significantly upregulated in brain and CNS, head and neck, kidney, liver, lung, skin, and prostate tumor samples compared to the normal samples (p-value = 0.05, fold change = 2)." (PMID 35601500, 2022).
renal carcinoma (1 paper, 2022). A carcinoma arising from the epithelium of the renal parenchyma or the renal pelvis. "As previously discussed, SHC1 protein expression was also upregulated in renal cancer, and the magnitude of regulation increased with the grades and stages in CPTAC-ccRCC samples." (PMID 35935986, 2022).
sarcoma (1 paper, 2024). A usually aggressive malignant neoplasm of the soft tissue or bone. "Consistently, we found a significantly positive correlation between the protein abundance of SHC1 and the TGFβ signaling pathway enrichment score (Pearson’s correlation, r = 0.15, p value = 0.028), suggesting an association between SHC1 and the TGFβ signaling in sarcoma." (PMID 38360860, 2024). "To test the clinical relevance of SHC1 targeting for HC1 (AS and ES), we collected 6 different sarcoma cell lines, including 2 AS cell lines (ISO-HAS and ASM), 2 ES cell lines (VA-ES-BJ and SU-CCS-1), and 2 WDLPS cell lines (93T449 and SW-872)." (PMID 38360860, 2024).
cancer (58 papers, 2008 to 2025). A tumor composed of atypical neoplastic, often pleomorphic cells that invade other tissues. "As a result, SHC1 is essential for cellular fitness, and its abnormal expression or enhanced activation has been linked to various diseases, most notably cancer." (PMID 40593476, 2025). "The upregulation of SHC1 activated immune-associated and cancer-related pathways, such as epithelial-mesenchymal transition, interferon-gamma response, inflammatory response, and the IL6/JAK/STAT3 pathway." (PMID 38763954, 2024). "When we explored the role of genes in different tumors, we found that genes such as RAC1 and SHC1 were elevated in most cancers, suggesting their role as prognostic risk factors in most tumors." (PMID 36969076, 2023). "Survival analysis of multiple databases showed that SHC1 expression was associated with poor prognosis in various cancers, especially in CESC, KICH, KIRC, KIRP, LGG, LIHC, LUAD, and UVM." (PMID 35601500, 2022). "This study assessed the relationship between SHC1 gene mutation and the prognosis of Pan-cancer through the cBioPortal database." (PMID 35601500, 2022). "The diagnostic value of SHC1 in various cancers of TCGA was investigated, then confirmed using the normal tissue of the GTEx dataset (controls)." (PMID 35601500, 2022). "We found that SHC1 was associated with abundant signaling pathways in pan-cancer, such as TNFA-NFKB, inflammatory response, IL6-JAK-STAT3, hypoxia, EMT, apical junction, and angiogenesis." (PMID 35935986, 2022). "SHC1 has prognostic and diagnostic value in a variety of cancers and may serve as a potential biomarker for cancer immunotherapy and diagnosis." (PMID 38632288, 2024). "Thus, SHC1 is a potential target for cancer immunotherapy and effective prognostic and diagnostic biomarker." (PMID 35601500, 2022). "A comprehensive analysis of the diagnostic value of SHC1 in pan-cancer was also conducted." (PMID 35601500, 2022). "Finally, we evaluated the potential diagnostic value of SHC1 across cancers to understand its underlying mechanisms in pathogenesis and clinical course of cancer." (PMID 35601500, 2022). "Additionally, based on the sites and number of cases of the SHC1 genetic alteration, we noted that missense mutation of SHC1 was the predominant form in various cancer types." (PMID 35601500, 2022). "Therefore, it is critical to implement a pan-cancer analysis to understand SHC1 copy number, mRNA and protein expression, and to evaluate its association with clinical outcomes and latent molecular mechanisms in cancer therapy." (PMID 35601500, 2022). "In summary, the simultaneous low expression of PLK1, phosphoMet, SGK2, and SHC1 might be associated with the immune response and tumor cell survival, which could result in poor survival outcomes in cancer progression." (PMID 34575686, 2021). "Thus, SHC1 as an effective prognostic and diagnostic biomarker may play a key role as a potential target for cancer immunotherapy." (PMID 35601500, 2022). "SHC1 regulates cancer growth owing to its tumor-specific activation, suggesting that it served as a useful predictive marker and a target for therapeutic intervention." (PMID 39391879, 2024). "Although no noteworthy cluster was found in upregulated genes unique to 9S1R-NulloPT treated cancer, Abl-1 and Shc-1 formed the center node of a small cluster." (PMID 37461536, 2023). "EGF/EGFR activation results in the separation of SHC‐binding protein 1 (SHCBP1) from SHC adaptor protein 1 (SHC1), which then translocates to the nucleus and promotes cancer development via multiple signaling pathways." (PMID 38107059, 2023). "Bioinformatics analysis revealed that elevated SHC1 expression served as a prognostic indicator for unfavorable outcomes in numerous cancer types." (PMID 37965333, 2023).
cancer (continued). "Taken together, our first pan-cancer study indicated that SHC1 expression was correlated with clinical outcomes, genetic mutation, TMB, MSI, DNA methylation, RNA methylation, protein phosphorylation, immune cell infiltration, and tumor-associated macrophage." (PMID 35601500, 2022). "Recent studies also found that SHC1 involved in tumor microenvironment and was a promising immunotherapy target for cancer treatment." (PMID 35601500, 2022). "In this study, we comprehensively investigated, for the first time, the SHC1 expression characteristics using a pan-cancer analysis of multi-database." (PMID 35601500, 2022). "We dichotomized the cancer cohort into high and low groups based on the median SHC1 mRNA-expression." (PMID 35601500, 2022). "SHC1 expression was positively correlated with the infiltration levels of six immune cells in various cancers, especially in PRAD." (PMID 35601500, 2022). "We found that high expression of SHC1 was generally strongly correlated with a worse prognosis in cancers (OS: total number = 9502, HR = 1.4, logrank p = 1.1e−16; DFS: total number = 9502, HR = 1.2, logrank p = 8.4E−06)." (PMID 35601500, 2022). "SHC1 protein (downregulated in MCF7 WWOXlow cells) sequesters ERK inhibiting MAPK/ERK pathway involved in cancer pathogenesis." (PMID 35290621, 2022). "We also evaluated the phosphorylation level of SHC1 in cancer and normal tissues, which indicated an increased level of phosphorylated SHC1 in ccRCC." (PMID 35935986, 2022). "The relationships between SHC1 expression and the outlook of each cancer type was determined using the PrognoScan web-based tool." (PMID 35601500, 2022). "More efforts are needed to explore the role of SHC1 in cancer and the value of SHC1 as a potential target of anticancer therapy." (PMID 35601500, 2022). "TIMER2.0 database was used to assess the correlation between SHC1 expression and the immune cell infiltration in pan-cancer." (PMID 35601500, 2022). "EGF/EGFR activation causes the detachment of SHC-binding protein 1 (SHCBP1) from SHC adapter protein 1 (SHC1), which subsequently translocates into the nucleus and promotes cancer development via multiple signaling pathways." (PMID 35013128, 2022). "Subsequently, the correlation between SHC1 expression and that of 30 common m6A RNA modification regulators with different types of cancer was evaluated." (PMID 35601500, 2022). "The gene with the second highest pathway contribution gene index was SHC1 (pathway contribution gene index = 0.904), which plays an important role in regulating cell apoptosis and drug resistance in numerous types of cancer." (PMID 34768960, 2021). "High-risk and advanced PCas shared the expression of diverse proteins that are reportedly associated with cancer progression, namely TGF-β, Wnt5a/b, Shc1 (phospho-SHCY317), phospho-c-RAF-S338 and phospho-c-MycT58/S62." (PMID 34155195, 2021). "In summary, taking a systems approach based on the cancer hallmark network framework, we found that the FFL (PDGF/FLT1/SHC1) is significantly enriched in the PIK3CA-mutated luminal-A tumor patients." (PMID 28392480, 2017). "RAC2 also showed upregulation of proliferative pathways, including signalling by NTRK2/TRKB, characterised by overexpression of the PIK3CA gene, and signalling by ERBB2 in cancer, as reflected by elevated serum concentrations of SHC1, ERBB4, EGFR and ERBB2, compared with RAC3." (PMID 39401856, 2024). "Deep investigation into SHC1 revealed that the gene was crucial for numerous cancer cells." (PMID 39391879, 2024). "Various small molecular proteins that induce changes in cell conformation also affect key downstream signaling pathways, such as the overactivation of the HER2-SHCBP1-PLK1 axis by SHC linker protein 1 (SHC1), representing a novel mechanism of cancer resistance to trastuzumab." (PMID 39655080, 2024). "Notably, bioinformatics analysis revealed that high expression of SHC1 as a prognostic factor displayed worse prognosis in many cancer types." (PMID 35601500, 2022).
cancer (continued). "Interestingly, TAMs (CCL2, CD86, and IL10), M1 [INOS(NOS2), IRF5, and COX2(PTGS2)] were significantly correlated with SHC1 expression in the three cancers." (PMID 35601500, 2022). "Increased SHC1 gene expression and its transcriptional signature are detected in many cancer types." (PMID 35601500, 2022). "Moreover, SHC1 expression was found to affect DSS in patients of seven cancer types, including ACC, BRCA, KIRP, LIHC, MESO, PAAD, and UCEC." (PMID 35601500, 2022). "In addition, the SHC1 gene expression across various cancer types in the TCGA were evaluated using TIMER2." (PMID 35601500, 2022). "SHC1 expression in cancers verus normal tissue in Oncomine database." (PMID 35601500, 2022). "Interestingly, CD276, NRP1, and TNFSF4 expressions were significantly negatively correlated with SHC1 in various cancers." (PMID 35601500, 2022). "The increasing expression of SHC1 could negatively regulate the T-cell activation and survival, which might result in poor survival outcomes in cancer patients." (PMID 34575686, 2021). "Knockdown of SHC1 in DEPDC1B-overexpressed cancer cells could abolish the promotion effects induced by DEPDC1B." (PMID 33203836, 2020). "A broad human TissueScan cancer survey panel was screened for expression of both SHC1 transcripts." (PMID 31202267, 2019). "The context in which activation of SHC1 preferentially regulates myeloid DC polarization versus cancer cell signaling remains unclear." (PMID 29871670, 2018). "Finally, enrichment analysis indicated that SHC1 may potentially involve in the regulation of numerous signaling pathways in cancer metabolism and protein phosphorylation-related functions." (PMID 35601500, 2022). "However, the relationship between reduced phosphorylation levels of SHC1, as a potential oncogenic factor, and the progression and prognosis of other cancers is unknown." (PMID 35601500, 2022). "Notably, we further identified multiple reported malignancy‐related genes (e.g., MET, PIK3R1, PRKCA, PTEN, SHC1, and STAT3) upregulated in HCC272, and demonstrated that these genes were mainly enriched for cancer‐related functions, which were associated with broad drug resistance." (PMID 34105295, 2021). "Knockdown of SHC1 could alleviate the cancer-promoting effect of DEPDC1B on BC." (PMID 34187252, 2021). "Moreover, the Kaplan‐Meier curve analysis of SHC1 methylation at specific probes and SHC1 expression revealed that SHC1 might act as a biomarker for the prognosis of these two kinds of carcinomas." (PMID 34117717, 2021). "Analysis of mRNA expression in TCGA paired samples revealed notably enhanced levels of LDHA, SHC1 and CDKN3 in cancer tissues compared to adjacent tissues, whereas PCSK9, BTK, CAV2 and PDGFB showed significantly reduced expression." (PMID 40182622, 2025). "In addition, SHC1 was also significantly associated with DNA methylation, m6A RNA methylation, tumor mutational burden (TMB), Mismatch repair proteins (MMRs), microsatellite instability (MSI), TAMs, tumor-associated immune cell infiltration, and immune checkpoints in cancers." (PMID 38602568, 2024). "The research has shown that cancer driver genes are often found together in the same modules instead of being randomly scattered, and this suggests that the identified cancer genes SHC1 and GRB2 are promising candidates for cancer driver genes." (PMID 39751645, 2024). "It is worth noting that among these genes, STAT3 is the known cancer driver gene, while SHC1 and GRB2 are cancer driver genes predicted by SGCD (ranked in the top 50 predicted cancer driver genes of MULTINET)." (PMID 39751645, 2024). "The relationship between SHC1 expression and OS, PFS, DFI, and DSS in 33 cancer types were shown by the forest plots." (PMID 35601500, 2022).